IL6 (interleukin 6)
Diseases named in the same sentence as IL6 in open-access papers (continued):
Sharing a sentence is not in itself a finding about the gene and the disease.
breast cancer (continued). "M2 macrophages can also facilitate STAT3 signaling in breast cancer cells to promote tumor proliferation, and STAT3 activation in M2-polarized macrophages can activate STAT3 signaling in ovarian cancer cells to promote their growth via the production of IL-6 and IL-10." (PMID 36010693, 2022). "Specifically, we found that PFKFB4 promotes angiogenesis via IL-6 (not via VEGF) in breast cancer." (PMID 34976184, 2022). "Interestingly, exosomal miR-9 and miR-181a were reported to promote breast cancer through the activation of the JAK/STAT signaling pathway and increasing the production of early myeloid-derived suppressor cells that express significant levels of IL-6." (PMID 36406206, 2022). "Additionally, AFI has been reported to have anticancer activities against human breast cancer cells (MCF-7) and lung cancer cells (HCC827) by stimulating the production of tumor necrosis factor-alpha (TNF-α), interleukin-6 (IL-6), and interleukin-1 beta (IL-1β)." (PMID 36059847, 2022). "Simultaneous inhibition of IL-6 and IL-8 receptors via Tocilizumab and Reparixin (inhibitor of C-X-C motif chemokine receptor 1) significantly decreased the expression of matrix metalloprotease in mouse MDA-MB-231 breast cancer model models and decreased the incidence of liver and lung metastasis." (PMID 36429126, 2022). "The EGFR inhibitors, which are principally used in non-small cell lung cancers or breast cancers, may act on SARS-CoV-2 virus replication, whereas JAK2 inhibitors could act on SARS-CoV-2 cytokine storm because IL-6 and GM-CSF, which are stimulated in this infection, depend on JAK2 signaling." (PMID 34864885, 2022). "In the presence of IL-6 and collagen within the tumor microenvironment, a subset of FAP+ TAM expressed cytokines consistent with a wound healing response observed in macrophages isolated from wounded skin, and this gene expression profile was correlated with poor prognosis in breast cancer patients." (PMID 35435599, 2022). "However, mammary carcinoma cells responded to poly(I:C) transfection with the upregulation of Cxcl10 and IL-6 but not TNFα mRNA levels." (PMID 35737804, 2022). "Furthermore, utilizing the combination of STAT3 suppressor with a poly ADP-ribose polymerase (PARP) suppressor, IL6/STAT3 activity could be targeted, resulting in the successful treatment of palbociclib resistance in breast cancer cells." (PMID 34488773, 2021). "Interestingly, cisplatin treatment upregulated IL-6 levels in ECs, and the resulting conditioned medium induced VM formation in MDA-MB-231 breast cancer cells that might eventually promote drug resistance and metastasis." (PMID 34359928, 2021). "The data suggested that IL6 and HOXA4 may play key roles in LumB-subtype breast cancer." (PMID 33644115, 2021). "The significance of the CDK4/6-DUB3 axis in regulating breast cancer metastasis has been confirmed by another study, demonstrating that the inhibitor of DUB3, WP1130, suppresses DUB3-mediated Snail1 stabilization and that IL-6 stabilizes Snail1 by activating DUB3." (PMID 34454495, 2021). "Thus, IL-6 and CRP may be involved in inflammatory pathways connected to breast cancer tumorigenesis." (PMID 33441805, 2021). "Moreover, IL-6 activated the STAT3 was specifically enriched in co-culture system between macrophages and breast cancer MCF-7 cells as compared to control, which also showed significant upregulation of transforming growth factor β (TGF-β1) and hypoxia-inducible factor-1α (HIF-1α) mRNA levels." (PMID 33957948, 2021). "In addition, all of the biochemical parameters we analysed were statistically significant in both breast cancer patients (NF-κB: p<0.001; sTRAIL: p<0.01; TNF-α: p<0.001; IL-6: p<0.001; PCT: p<0.001; PTX-3: p<0.001; CRP: p<0.001) and colon cancer patients (for all p<0.001) compared to the control." (PMID 33776564, 2021).
breast cancer (continued). "Similarly, subjects with CRP levels >ULN were more likely to have relapsed breast cancer (OR 2.66, 95% CI 1.34–5.28, p = 0.005), while subjects with IL-6 levels >ULN had no increased likelihood of relapsed breast cancer (OR 0.62, 95% CI 0.20–1.90, p = 0.402)." (PMID 33483516, 2021). "However, up to now, IL-6-based therapies have demonstrated no clinical efficacy in breast cancers and also in other various types of cancer patients." (PMID 34445170, 2021). "Interestingly, the expression of cytokines in both types of breast cancer cell lines differed significantly e.g., ME significantly enhanced the expression of IL-1β and IL-6 genes in MCF-7 cells, whereas we did not observe such an effect in 4T1 cells." (PMID 34201348, 2021). "Arid5a under IL6 signaling binds to the upstream region of a lncRNA, AU021063, and transcriptionally upregulates the expression of this noncoding RNA, which further leads to the enhanced invasion and metastasis of breast cancer cells in mice by stabilizing the tribbles homolog 3 (Trib3) protein." (PMID 35126382, 2021). "Using RT-PCR to examine expression levels of genes in circulating leukocytes, it was shown that TNF-alpha, IL-6, leptin and ErbB2, were significantly higher in obese individuals without a cancer diagnosis and among breast cancer patients compared to the lean group." (PMID 33597950, 2020). "Similarly, an increase in osteoblast derived cytokines (e.g., IL-6, IL-8, MCP-1, macrophage-inflammatory protein 2 (MIP-2), and vascular endothelial growth factor (VEGF)) has been identified upon the presence of MDA-MB-231 breast cancer cells." (PMID 32092997, 2020). "Some of these cytokines, such as IL-1, IL-6, IL-11, and transforming growth factor (TGF)-β, stimulate breast cancer proliferation and invasion, whereas other cytokines such as IL-12p70, IL-18, and IFNs exert opposite effects on breast cancer proliferation or invasion." (PMID 32703187, 2020). "It is therefore not surprising that the ectopic expression of IL-6 or treatment with recombinant IL-6 in ER+ breast cancer cells significantly increases the expression of EMT-related genes through STAT3, leading to increases in tumor cell proliferation in orthotopic xenograft models." (PMID 32023849, 2020). "Genetic analysis of DCCs revealed that DCCs from HR+ breast cancer progressing to manifest metastasis often acquired PIK3CA mutations, possibly because the activated PI3K/AKT pathway rendered mammary epithelial cells independent of IL-6 trans-signaling." (PMID 33020483, 2020). "Previous efforts to identify mechanisms of resistance to CDK4/6 inhibition have found that lack of Rb protein, increased cyclin E expression, IL6/STAT3 pathway activation and decreased DNA repair are some of the underlying mechanisms of resistance in ER+ breast cancer cells." (PMID 32344635, 2020). "In solid tumors, including prostate cancer and breast cancer, STAT3 activation which was mediated by IL-6 could enhance the expression of anti-apoptotic proteins, such as BCL2 or survivin which has constantly been regarded as a protective mechanism from chemotherapy-induced cell death." (PMID 32391256, 2020). "Also, human breast cancer survivors who participated in a six month endurance training intervention had significant reductions in serum levels of systemic inflammatory cytokines such as TNF-α and IL-6." (PMID 32542046, 2020). "Other examples proving the molecular similarity between dormant DCCs and CSCs include the interleukin 6 (IL-6) cytokine leukemia inhibitory factor (LIF)-LIF receptor (LIFR) axis, which appears to have a role in preserving both dormancy and cancer stemness, at least in the breast cancer setting." (PMID 33193295, 2020). "The authors showed how the inhibition of IL-6/IL-6R signaling by IL-6 siRNA suppressed angiogenesis/invasion by up-regulating MAO-A expression, a mitochondrial protein that commonly degrades monoamines and is usually found down-regulated in multiple cancers, including breast carcinoma." (PMID 33322132, 2020).
breast cancer (continued). "Additionally, IL6 has been shown to function as a molecular switch between non‐CSCs and CSCs in breast cancer, suggesting a dynamic system that is dependent on communication between the different cell types through secretion to maintain the CSC niche." (PMID 31066211, 2019). "Our results reveal that JAK2/PAK1 dysregulation inhibits the Stat3 signaling pathway and CSC formation, the PAK1/Stat3 complex regulates IL-6 gene expression, PAK1/Stat3 signaling regulates CSC formation, and PAK1 may be an important target for treating breast cancer." (PMID 31658701, 2019). "CAAs secrete more chemokine (C–C motif) ligand 2 (CCL2), chemokine (C–C motif) ligand 5 (CCL5), interleukin-1β (IL-1β), interleukin-6 (IL-6), tumor necrosis factor-alpha (TNF-α), vascular endothelial growth factor (VEGF), leptin, etc., which can promote the invasion and metastasis of breast cancer." (PMID 31500658, 2019). "As opposed to the role of the IL-6 inflammatory loop in inducing CSCs with mesenchymal features in breast cancer, IL-8 mainly regulates a subpopulation of epithelial-like CSCs that express high aldehyde dehydrogenase (ALDH) activity and are highly proliferative." (PMID 31417869, 2019). "In another study, functional inhibition of the subgroup of IL-6- and IL-8-secreting CD10+GPR-77+ CAFs with anti-IL-6 and anti-IL-8 antibodies, together with docetaxel chemotherapy, has led to a near complete remission of tumors in a patient-derived xenograft (PDX) model of breast cancer." (PMID 31417869, 2019). "Hence, identifying drugs that can inhibit IL-6/STAT3 signalling may present an opportunity to inhibit adipocyte-induced EMT and invasion in breast cancer cells." (PMID 31383893, 2019). "In addition, estrogen influences the production of cytokines and growth factors, such as insulin-like growth factor (IFG-1), interleukin-6 (IL-6), osteoprotegerin (OPG), and receptor activator of nuclear factor kappa-B ligand (RANKL), which are involved in bone turnover and mammary cancer." (PMID 31240225, 2019). "Importantly, we confirm that OSM induces at least a 4-fold increase in IL-6 production from estrogen receptor-negative (ER−) breast cancer cells in a manner that is dependent on STAT3 signaling." (PMID 31007849, 2019). "Interestingly, our in vitro results demonstrated that OSM induced IL-6 in breast cancer cells in an ER−dependent manner, while OSM did not promote secretion of IL-6 in ER+ cell lines." (PMID 31007849, 2019). "JAK1 is essential for IL-6-class inflammatory cytokine signaling, plays a critical role in metastatic cancer progression, and mediates the persistent oncogenic activation of STAT3 in mammary cancer cells that are driven by ERBB2 receptor tyrosine kinase signaling." (PMID 31790361, 2019). "IL-6 secretion is crucial for CSC maintenance and sufficient to induce the CD44 + /CD24 low phenotype in breast cancer cell lines and tumors, this supporting the idea that the IL-6-JAK2-STAT3 signal transduction pathway could play an important role in the conversion of non-CSCs into CSCs." (PMID 30728463, 2019). "Several preclinical studies showed that metastatic breast cancer cells, directly or through Jagged1-expressing tumor cells, induced osteoblasts to express high levels of IL-6, while they seemed to not affect IL-6 production by osteoclasts." (PMID 31847214, 2019). "To this end, we examined the METABRIC breast cancer dataset for the expression of a signature composed of the genes belonging to the IL-6 or the WNT non-canonical pathways characterized by in vivo binding of both STAT3 and SP1, as identified above, denominated the SP1-S3 signature." (PMID 30654518, 2019). "The mouse mammary carcinoma 4T1 cells in the present study showed remarkable resistance to DOX and two mechanisms of resistance have been clearly identified i.e. induction of P-gp mediated drug export and upregulation of the pro-survival, anti-apoptotic interleukin 6 (IL-6)." (PMID 31623629, 2019).
breast cancer (continued). "Therefore, osteoblast secretion of IL-6, IL-8, MCP-1, GRO-alpha, and VEGF contributes to osteoclast bone resorption independently of RANK-L in the classic ‘vicious cycle’ model, as well as promotes breast cancer survival in bone." (PMID 29867053, 2018). "The relevance of the non-canonical-Notch/NF-κB/IL-6 axis stems from the evidence that, while canonical Notch4 is necessary for the development of mammary glands, non-canonical Notch4 signaling is related to breast cancer tumorigenesis." (PMID 30154786, 2018). "Moreover, the IL-6/STAT3 signaling pathway might be a promising candidate target in developing novel therapeutic strategies to eliminate e-MDSCs and improve breast cancer prognosis." (PMID 30083161, 2018). "Furthermore, the IL-6/STAT3 signaling pathway could be a promising candidate target in developing novel therapeutic strategies to eliminate e-MDSCs and improve breast cancer prognosis." (PMID 30083161, 2018). "(A-C) Boxplot representation of IL-6 (A) (Student’s t test, P < 2.2 × 10− 16), CCL2 (B) (Student’s t test, P < 2.2 × 10− 16), and MMP9 (C) (Student’s t test, P < 2.2 × 10− 16) expression levels in ER+/PR+ breast cancer compared to triple-negative breast cancer (TNBC)." (PMID 30458886, 2018). "Furthermore, interference of YAP nuclear translocation using the statin cerivastatin reverses the upregulation of Interleukin 6 (IL-6) and the pro-invasive effect of RA on MDA-MB-231 breast cancer cells and also decreases invasion and viability of MDA-MB-468 breast cancer cells." (PMID 29728589, 2018). "Others have confirmed later that activation by interleukin IL-6 (IL-6) of JAK1-STAT3-OCT4 pathway may convert differentiated breast cells (non-cancer stem cells) into breast cancer stem cells." (PMID 30486884, 2018). "However, in agreement with our previous findings, we did not observe significant effects of IL-6 on anchorage-dependent and -independent breast cancer cell growth." (PMID 29707128, 2018). "Indeed, a recent study demonstrated that inducible IκB kinase-related (IKK-related) kinase IKBKE promotes in triple negative breast cancer cells the expression of IL-6 and CCL5, which in turn sustain the proliferation and migration of breast cancer cells in 3D culture." (PMID 29707128, 2018). "Furthermore, a stable equilibrium between BCSC and non-stem breast cancer cells was maintained by the amount of IL-6 secreted by BCSCs, expression level of IL-6 receptor and the whole response of non-BCSC to IL-6." (PMID 30175384, 2018). "Exosomes derived from breast carcinomas, for instance, were shown to be taken up by bone marrow cells and to switch the differentiation pathways of these cells toward MDSCs via Prostaglandin E2 and TGF-β, promoting accumulation of COX2, IL6, VEGF and Arginase1 by MDSCs." (PMID 29515996, 2018). "When compared to the mouse mammary carcinoma cell line EMT6, 4T1 cells exhibit higher levels of IL-6 expression in culture, and in a series of experiments using these two cell lines, it has been demonstrated that IL-6 expression positively impacts the recruitment of MDSCs and metastatic potential." (PMID 29875329, 2018). "This indicates that IL-6 trans-signaling is predominately mediated by soluble CD126 to regulate IL-6-dependent SOCS3 suppression and sustained activation of the JAK/STAT pathway in MDSCs, as well as coordinates the differentiation and immunosuppressive activity of MDSCs in breast cancer." (PMID 29326716, 2017). "FTO rs3751812 and IL-6 rs1800796 did not change either OS or PFS of breast cancer." (PMID 28591216, 2017). "Indeed, survivors of breast cancer frequently show significant cognitive damage, and notably, findings from a study with breast cancer patients showed evidence of TNF-α and IL-6-mediated altered hippocampal volume and verbal memory difficulties following chemotherapy." (PMID 29202842, 2017).
breast cancer (continued). "Thus, NZ, by reducing IL-6 s and completely abolishing CCL5 secretion by MSCs may counteract the consequences of MSCs/PCa and MSCs/breast cancer interactions." (PMID 28477013, 2017). "Furthermore, breast cancer cells that were sensitive to drug treatment did not express IL-6, whereas multidrug-resistant breast cancer cells produced high levels of IL-6." (PMID 29527228, 2017). "Among women with CC genotype of IL-6 rs1800796 or GG genotype of HSPD1 rs2605039, diabetic individuals had a remarkably increased risk of breast cancer compared to non-diabetic women with ORs and 95%CIs of 2.53 (1.45, 4.41) and 6.40 (2.29, 17.87), respectively." (PMID 28591216, 2017). "A knockdown (KD) of TG2 in breast cancer cells expressing high levels of TG2 reduced IL-6 expression, moreover, TG2 KD and IL-6 KD cells did not exhibit a stem-cell-like phenotype and were unable to form tumor spheres, grow in vivo, or metastasize at distant sites in xenograft models." (PMID 27609180, 2016). "Simple overexpression of TG2 in MCF7 luminal-type breast cancer cells did not lead to IL-6 expression, so we then investigated additional signaling pathways that may elicit cancer cell aggressiveness through IL-6 induction." (PMID 27609180, 2016). "In addition to another HER2-positive PDX, we selected four triple negative PDXs, we chose this subtype because it has been shown that it also depends on IL-6 signaling to grow and it is the only subtype of breast cancer without targeted therapy." (PMID 27602583, 2016). "In breast cancer cells, TG2 overexpression conferred EMT and stem-cell-like phenotypes, and IL-1β treatment increased stem-cell-like phenotypes, invasion, and estrogen-independent tumor growth in a TG2-dependent manner, which was attenuated by either anti-IL-6 or anti-IL-1β antibody treatment." (PMID 27609180, 2016). "Triple negative breast cancers rely on the autocrine expression of IL-6 for growth." (PMID 26840088, 2016). "Interestingly, proliferation of ER- breast cancer cells are not affected by IL-6 implying IL-6-independent modulation of ER- MDA-MB-231 cells proliferation." (PMID 27101408, 2016). "Recently, a clinical study reported that IL-6 and sIL-6R levels were significantly higher after the conclusion of chemotherapy in breast cancer patients with CIPN than in those without CIPN, providing the first clinical evidence of the involvement of IL-6 in CIPN." (PMID 27267059, 2016). "In addition, IL-6 was shown to induce breast cancer stem cell formation from non-stem cancer cells through an autocrine/paracrine mechanism and to regulate epigenetic modification of microRNAs in malignant human cholangiocarcinoma." (PMID 27285760, 2016). "Therefore, IL-1β in the tumor microenvironment and tumor cell TG2 and IL-6/STAT3 signaling pathway may be potential targets for combating recurrent and therapy-resistant luminal-type breast cancer." (PMID 27609180, 2016). "Moreover, inflammatory cytokines, such as interleukin (IL)-6, induce LCN2 expression depending on activation of the STAT3 signaling pathway, IL-1β and the tumor cell-derived factor IL-10 also promote LCN2 expression in lung and breast cancer." (PMID 27912767, 2016). "Finally, using a publicly available data site (R2: microarray analysis and visualization platform; Tumor breast EXPO-351) with gene expression profiles of 351 primary breast cancers, we found positive correlation between expression of TLR4 mRNA and IL-6 (r value 0.231, P = 1.3e-05)." (PMID 26392082, 2015). "Therefore, the key role of FN1, IL6 and FOS in breast cancer development has been demonstrated." (PMID 25824986, 2015). "IL-6 signaling pathways occur early in the inflammatory cascade with subsequent downstream effects on insulin-signaling molecules and insulin pathways (e.g., IGF-1), which may be related to weight gain, recurrence, and survival of patient with breast cancer." (PMID 25793000, 2015).